AR (androgen receptor)
Diseases named in the same sentence as AR in open-access papers (continued):
Sharing a sentence is not in itself a finding about the gene and the disease.
breast carcinoma (continued). "The expression of Lin28A and AR were examined after Lin28A siRNA and Lin28A plasmid were transfected into ER−/Her2+ breast cancer cells." (PMID 27494865, 2016). "Our present study was aimed to determine the prevalence of AR expression and its relationship with some clinical and pathological parameters in Thai breast cancer patients." (PMID 29083379, 2016). "The aim of this study was to investigate prevalence and related factors of androgen receptor (AR) expression in Thai breast cancer patients." (PMID 29083379, 2016). "Our findings are also in line with previous observations from breast cancer, where the prognosticvalue of AR is improved by combining AR and ERα status." (PMID 27384477, 2016). "Having previously demonstrated the co-expression status of Lin28A and androgen receptor (AR) in ER−/Her2+ breast cancer, this study showed that Lin28A can induce the expression of AR via regulation of c-myc in ER−/Her2+ breast cancer." (PMID 27494865, 2016). "Here we sought to determine if ADT, with enzalutamide or abiraterone, was capable of increasing the sensitivity of breast cancer cells to immune-mediated lysis and, if so, was this effect also dependent on AR expression." (PMID 27015557, 2016). "Tilley and colleagues using MCF-7 and T47D ER- and AR- positive luminal breast cancer cell lines demonstrated that two steroidal androgens (DHT and mibolerone) inhibited the cell proliferation." (PMID 27918430, 2016). "We evaluated the ability of AR inhibition to reduce the growth and improve the immune-mediated killing of breast cancer cells with differing expression of the estrogen receptor and AR." (PMID 27015557, 2016). "Below we summarize the clinical and preclinical evidence supporting the use of both AR agonists and antagonists as treatment options for breast cancer." (PMID 27918430, 2016). "Taken together, these data demonstrated the functional importance of Lin28A and AR in human ER−/Her2+ breast cancer." (PMID 27494865, 2016). "In lineage-specific analysis of breast cancer cell lines we demonstrated, for the first time, a role for AR expression in the response of breast cancer cells to ionizing radiation, mainly by preventing DNA damage." (PMID 27109210, 2016). "Although its role in breast oncogenesis remains poorly defined, AR is detected in a majority of breast carcinomas at levels greater than normal breast levels." (PMID 27109210, 2016). "The ability of enzalutamide to reduce the growth rate of breast cancer cells has been shown to be strictly dependent on their expression of AR." (PMID 27015557, 2016). "We transfected Lin28A siRNA and Lin28A plasmid transiently into ER−/Her2+ breast cancer cells and found that increase of AR expression can enhances growth, invasion, and soft agar colony formation." (PMID 27494865, 2016). "To exclude the influence of specific factors present in MCF-7 cells, we measured miR-21 expression in other two AR positive breast cancer cells, SK-BR-3 and ZR-75-1, evaluating the ability to repress luciferase expression when the miR is expressed." (PMID 26862856, 2016). "Our data provide evidence that in breast cancer cells activated AR is a transcriptional repressor of miR-21 expression." (PMID 26862856, 2016). "Noticeably, the Thai triple negative breast cancer patients had a lower expression of the AR (33%) compared to Western patients (40%–50%), but AR expression observed in our study was comparable with that reported for Chinese breast cancer patients (28%)." (PMID 29083379, 2016). "Androgen receptor (AR) inhibition has displayed efficacy against breast cancer preclinically and is currently being examined clinically in AR positive TNBC patients." (PMID 27015557, 2016). "Having confirmed the ability of androgens to counteract miR-21 induced breast cancer cell growth by reducing miR-21 expression, we evaluated if AR was involved in the down regulation of miR-21." (PMID 26862856, 2016).
breast carcinoma (continued). "For ER+/AR+ breast cancer cell lines, AR activation had anti-proliferative effect; in contrast, it induced pro-proliferative effect for ER-/AR+ cell lines." (PMID 27374089, 2016). "We found that breast cancers expressing the estrogen receptor (ER) are more likely to co-express AR compared to ER-negative cancers (56.0% versus 28.1%, P < 0.001)." (PMID 27285752, 2016). "For example, a study conducted in a Chinese cohort of 450 breast cancer patients showed that AR expression correlated with an increase in DFS in luminal breast cancer patients but a decrease in DFS in patients with TNBC." (PMID 27918430, 2016). "Most of the AR-negative breast cancer patients were younger and had higher Ki67 compared to AR-positive breast cancer patients." (PMID 27918430, 2016). "Several studies using natural androgens demonstrated that the breast cancers regressed by 30%–50% in pre- and in post-menopausal women and that these effects were predominant in breast cancers expressing the AR." (PMID 27918430, 2016). "One of the breast cancer subtypes where AR’s prognostic value was debated is the molecular apocrine type." (PMID 27918430, 2016). "IGF1R is a member of insulin receptor family and it has been shown that in prostate and breast cancer cells AR binds to IGF1R promoter and thus increases IGF1R expression." (PMID 27993167, 2016). "Ironically, both nonsteroidal agonists and antagonists for the AR are undergoing clinical trials, making AR a complicated target to understand in breast cancer." (PMID 27918430, 2016). "In summary, we show that Lin28A plays an important activating role in the AR expression via c-myc and thereby promotes ER-/Her2+ breast cancer cell prolification and invasiveness." (PMID 27494865, 2016). "In fact, studies have shown significant differences of the AR actions between breast and prostate cells and, thus, data from the prostate cannot be directly extrapolated to breast cancer." (PMID 26797644, 2016). "Cochrane et. al. found that a high AR to ERα ratio was an independent predictor of disease-free and disease specific survival in breast cancer." (PMID 27384477, 2016). "A single-arm phase II is currently assessing the more potent AR antagonist, enzalutamide (ENZ), in women with advanced, AR-positive, ER/PR-negative breast cancer." (PMID 27109210, 2016). "Recently, also in breast cancer treatment, targeting AR has been suggested beneficiary for specific subgroups of patients." (PMID 27384477, 2016). "The aim of this study was to clarify, based on AR expression in patients with breast cancer, the differences in chemosensitivity, clinically and pathologically." (PMID 26757422, 2016). "Perhaps surprisingly, the AR is the most widely expressed nuclear hormone receptor in breast cancer with about 85%–95% of the ER-positive and 15%–70% of the ER-negative breast cancers expressing AR." (PMID 27918430, 2016). "Here we demonstrated that AR inhibits breast cancer cell growth by down-regulating miR-21 expression." (PMID 26862856, 2016). "Such event is associated to a significantly reduced PolII binding in Mib treated extracts confirming that activated AR is a transcriptional repressor of miR-21 expression, providing further insight into the protective role of androgens in breast cancer cells." (PMID 26862856, 2016). "Lin28A introduces AR expression and activity in ER-/Her2+ breast cancer cells by targeting its transcription via c-myc." (PMID 27494865, 2016). "We previously showed, using a co-culture model of human breast tumor cells with primary breast fibroblasts, that some androgens can indeed inhibit breast cancer cell growth via the AR." (PMID 29083379, 2016). "All these in vitro and in vivo results in multiple models unequivocally prove that AR agonists are inhibitors of ER-positive luminal breast cancers." (PMID 27918430, 2016).
breast carcinoma (continued). "Recent studies have found that androgen receptor (AR) is highly expressed in ER-/Her2+ breast tumors and androgens and AR stimulate the growth of ER−/Her2+ breast cancer cells by activating oncogenic Wnt signaling pathways." (PMID 27494865, 2016). "The aim of this study was to clarify the differences in chemosensitivity, clinically and pathologically, based on AR expression in patients with breast cancer." (PMID 26757422, 2016). "One of the unique features of the molecular apocrine breast cancers is that they express AR, potentially making AR a valuable prognostic and therapeutic target." (PMID 27918430, 2016). "For example, the ground truth of the sentence ‘L-plastin gene expression was positively regulated by testosterone in AR-positive prostate and breast cancer cells’." (PMID 27173520, 2016). "Compared with ER or PR in breast cancers, few researches are conducted for the roles of androgen and androgen receptor (AR) in breast cancers." (PMID 25695063, 2015). "Meta-analysis of combined PSAP and AR mRNA are indicative of poor disease-free survival in endocrine treated breast cancer patients (hazard ratio (HR): 2.2, P = 0.0003, n = 661)." (PMID 26341737, 2015). "In a panel of breast cancer cell lines it was shown that endocrine resistant cells exhibit innately elevated levels of AR compared to their endocrine sensitive counterparts." (PMID 26341737, 2015). "Traditionally, estrogen receptor (ER) and progesterone receptor (PR) are known to be the prominent players in the progression and development of breast cancer but recent evidences suggest an important role of AR in breast cancer progression as well." (PMID 25781993, 2015). "AR, a member of the steroid hormone receptor family, is reported to be expressed in more than 70% of breast cancer and detected only in 25–35% of TNBCs." (PMID 25695063, 2015). "Further analysis of TCGA datasets also demonstrate a correlation between HOXC11 and PSAP transcript levels, specifically in luminal B breast cancer in which AR is elevated (rs = 0.46)." (PMID 26341737, 2015). "Here, we demonstrate that stimulation with PSAP can drive AR recruitment to a hormone response element (HRE) in AI resistant breast cancer cells." (PMID 26341737, 2015). "All these evidences suggest that understanding AR signalling will provide the rationale for targeting of different types of breast cancer cells for the purpose of therapeutic intervention." (PMID 25781993, 2015). "Meanwhile, interaction between AR and the MAPK pathway has been demonstrated with HER2-AR-ERK feedback loops in breast cancer." (PMID 25595907, 2015). "Dual label immunofluorescence revealed that AR-V7 and AR-FL proteins predominantly co-localized in the nuclei of breast cancer cells." (PMID 26554309, 2015). "Recent literature suggests that AR is emerging as a interesting target for breast cancer therapy in ER-/AR+ tumors and some triple negative breast cancers (TNBCs), which are enriched for AR signalling pathways." (PMID 25781993, 2015). "Other preclinical studies in human breast cancer cell lines showed that AR overexpression induced tamoxifen resistance which was reversed by the AR antagonist bicalutamide [S118]." (PMID 25595907, 2015). "Despite the prevalence of AR expression in both normal breast tissue and primary tumors, its clinical role in breast cancer is less well known." (PMID 26039245, 2015). "Taken together, our results provide new insights into the mechanism by which AR promotes breast cancer progression." (PMID 25781993, 2015). "Recent evidences suggest that AR antagonizes ER function and plays an anti-proliferative role in ER+ve breast cancers whereas it plays a significant role in facilitating tumor cell growth in an androgen-dependent manner in an ER–/AR+ breast cancers." (PMID 25781993, 2015).
breast carcinoma (continued). "The majority of research articles investigating the role of AR and/or androgens in breast cancer have concluded that male sex hormones and receptors have an inhibitory impact on breast cancer cell growth." (PMID 26341737, 2015). "The importance of androgen receptor (AR) signaling is increasingly being recognized in breast cancer, which has elicited clinical trials aimed at assessing the efficacy of androgen deprivation therapy (ADT) for metastatic disease." (PMID 26554309, 2015). "The androgen receptor is expressed in most breast cancers, including TNBC (70%) and its role in TNBC has recently been reviewed." (PMID 26633365, 2015). "In ERBB2-overexpressing breast cancer cells, beta-catenin co-activates AR to drive transcription of several tumor-promoting targets, including ERBB3 {{}}." (PMID 26509276, 2015). "MDA-MB-453 cancer cell line was chosen as the breast cancer model as it is a triple negative cell line having ER–/AR+ phenotype and it was experimentally verified that Her2 expression is not there in MDA-MB-453 cells by IHC staining." (PMID 25781993, 2015). "In contrast, in breast cancer MCF-7 cells expressing an AR as well as estrogen receptors, ELK1 overexpression reduced their colony formation." (PMID 26342199, 2015). "The actions of ER, Progesterone Receptor (PR), and Androgen Receptor (AR) in mediating breast cancer growth are well described in the literature." (PMID 26300846, 2015). "CA1 plays important roles in the calcification, apoptosis and migration of tumour cells and contributes to breast cancer tumourigenesis by regulating the expression of AR and XBP1." (PMID 26459317, 2015). "Approximately 75 % of breast cancers also express androgen receptor, which includes a proportion of triple-negative tumours." (PMID 26341737, 2015). "Gene expression profiling of the AR targets was done in MDA-MB-453 breast cancer cell line after steroid depletion for 24 hrs followed by stimulation with DHT for 4, 8, 12 and 24 hrs." (PMID 25781993, 2015). "Gene cluster B contained ERα and a group of NRs previously associated with ERα in breast cancer, including PGR, AR, RARα, LRH-1, PNR, as well as TRβ, RORβ, and RORγ." (PMID 26280373, 2015). "Literature suggested that AR signalling promotes outgrowth of neurite and also the neurite like outgrowth of breast cancer cells promotes tumour growth and metastasis." (PMID 25781993, 2015). "This would support the rationale for selective AR activation as a potentially attractive therapeutic approach for breast cancer." (PMID 26213785, 2015). "A recent systematic meta-analysis of 19 different studies showed that the expression of AR is favorable prognostic marker in early stage breast cancer, irrespective the ER status, with approximately a doubling of OS at 3 ad 5 years." (PMID 26039245, 2015). "Third, the known auto-regulatory activity of ligand-bound AR-FL on its own gene was functional in breast cancer cells, since DHT decreased whereas enzalutamide increased AR gene transcription." (PMID 26554309, 2015). "In a phase 2 study, in patients with ER/PR-negative and androgen receptor positive advanced breast cancer, the anti-androgen agent bicalutaminde has shown a 6 month clinical benefit rate of 19% and the median progression-free survival was 12 weeks." (PMID 26633365, 2015). "Further investigations into the AR transcriptome in AI-resistant breast cancer will help elucidate which processes are being impacted." (PMID 26341737, 2015). "Significant differences in AR expression were observed between the different subtypes of breast cancer, in fact high expression levels of AR were observed in the ER and / or PgR positive one and low in the TN." (PMID 26039245, 2015). "Emerging research suggests that the activation of the AR is able to inhibit breast cancer progression, and its expression is a significant prognostic marker in estrogen receptor positive breast cancers." (PMID 25883673, 2015).
breast carcinoma (continued). "The molecular apocrine phenotype is a characteristic of androgen receptor (AR)-positive breast cancers." (PMID 25592291, 2015). "A higher number of breast carcinomas were found to express AR (77%) compared to ER (61%) and PR (60%) in 980 cases, with more than 50% of triple negative tumors expressing AR [S113]." (PMID 25595907, 2015). "Various efforts to streamline the testing of AR in breast cancer and develop effective AR targeting treatment are currently made by researchers." (PMID 25973541, 2015). "With the advent of new and more efficient anti-androgen drugs targeting androgen receptor (AR) in breast cancer (BC) is becoming an increasingly important area of investigation." (PMID 26552477, 2015). "In mammary tumors from Postn-null mice, we have observed an increase in AR levels and an upregulation of its target genes PIP and Abp." (PMID 25592291, 2015). "Beside the hormone receptors ER and PR, more than 70% of primary breast cancers express the androgen receptor (AR)." (PMID 25510351, 2014). "AR transactivation assays demonstrated that SARMs are agonists in breast cancer cells and their IC50s and rank order were comparable to the transactivation results obtained in HEK-293 cells or COS-1 cells." (PMID 25072326, 2014). "SARM treatment inhibited the intratumoral expression of genes and pathways that promote breast cancer development through its actions on the AR." (PMID 25072326, 2014). "In the analysis, we considered the expression levels of AR in the major different subtypes of breast cancer." (PMID 24505496, 2014). "AR is expressed in 70-90% of breast cancers, but clinical testing of anti-androgen therapy in unselected patients with breast cancer met with little success." (PMID 25349530, 2014). "Based on these intriguing results in the small neoadjuvant study, we decided to examine the amount of AR relative to ER in the larger cohort of 192 female patients diagnosed with ER + breast cancer that received adjuvant tamoxifen therapy." (PMID 24451109, 2014). "Its expression is particularly high in the luminal A and androgen receptor (AR)-positive HER2-enriched breast cancer subtypes." (PMID 23755096, 2014). "To test the significance of AR and ER expression in breast cancer, we examined primary tumors from a group of tamoxifen-treated patients with clinical outcome data." (PMID 24451109, 2014). "Using the human cancer genome atlas database and two independent breast cancer cohorts we find that L1CAM is inversely correlated with androgen receptor (AR) expression." (PMID 25510351, 2014). "Correspondingly, the molecular apocrine type in breast cancer defined as ER-negative and AR-positive breast cancer showed significant overlap with the HER-2-enriched group on gene profiling analysis." (PMID 24884785, 2014). "The DS domain has been proved to be required for a series of important functions, including the regulation of cancer stem cell expansion, AR, IL-8 secretion and breast cancer cell invasion." (PMID 25322986, 2014). "The MDA-MB-453 breast cancer cell line obtained from a malignant pleural effusion of a 48-year-old female is characterized by AR+/ER-/PR-/HER2- profile is often used as a model to study the molecular processes underlying apocrine breast malignancy." (PMID 25389781, 2014). "The AR is the most prevalent sex steroid receptor occurring in up to 90% of all breast cancers (in situ and invasive disease including early and metastatic setting) and in a lower rate in TNBC (0%–53%)." (PMID 24978437, 2014). "Chromatin immunoprecipitation sequencing (ChIP-seq) and microarray expression profiling has revealed significant cross-talk in gene regulation between AR and ERα in ZR-75-1 human breast cancer cells." (PMID 24534923, 2014). "This bicalutamide-mediated increase in E2-stimulated proliferation was interpreted as indicating that AR is protective against E2-mediated breast cancer cell proliferation." (PMID 24451109, 2014).